CD4 (CD4 molecule)
Diseases named in the same sentence as CD4 in open-access papers (continued):
Sharing a sentence is not in itself a finding about the gene and the disease.
tumor (continued). "We assessed the intracellular production of IFNγ by intracellular staining (ICS) and confirmed the significant increase in its expression in both CD4+ Th and CD8+ T-cells in all tumor-bearing mice." (PMID 36555468, 2022). "In particular, the CSC marker CD44 was positively associated with immune markers, such as CD163, indicating a role of M2 macrophages in tumour dedifferentiation, or CD3 and CD4, which are indicative of an immune response." (PMID 36358805, 2022). "In the context of tumor immune response, the TR-DDR score strongly positively correlates with the number of T cells (CD4+ activated memory cells, CD8+ cells, T regs, Tfh) and macrophages M1 polarization." (PMID 36081518, 2022). "The stacked bar chart of CD3, CD4 and CD8 staining in 20 patients with PTC-WO and 20 patients with PTC-W showed that the numbers of CD3+, CD4+ and CD8+ T cells of tumor and normal samples in PTC-W were significantly higher than those in PTC-WO." (PMID 35720279, 2022). "CD4+ Th1 effector cells, by producing key cytokines such as IFN-γ, TNF-α, and IL-2, are critical players in anti-tumor protection, able to mediate cancer cell elimination through activation of both innate and adaptive immunity." (PMID 36428727, 2022). "Highly significant correlations (P < 0.0001 for all markers) were observed for ER (tumor R = 0.76), Ki‐67 (tumor R = 0.41), CD4 (tumor R = 0.34, stroma R = 0.52), and CD8 (tumor R = 0.48, stroma R = 0.56)." (PMID 34018684, 2022). "These simultaneous actions stimulate the adaptive immune system, including helper CD4+ T cells and cytotoxic CD8+ T cells, toward the tumor resulting in disabling the tumor immunosuppression." (PMID 35273607, 2022). "We next explored other marker expressions between the tumor-PB pairs and found higher CD57+ expression in the tumor CD4+ T cells, whereas in the NK cells, higher expression was observed in the PB samples." (PMID 35003893, 2022). "The percentage of exhausted CD4+ T cells, described as TIM3+LAG3+, was reduced in spleens and pulmonary tumors by depletion of tumor cell–autonomous SHP2." (PMID 36969745, 2022). "Again, an increased frequency of CD4+ and CD8+ T cells expressing CD56 was observed in tumor samples with a desmoplastic growth pattern (p < 0.0001)." (PMID 36551555, 2022). "In contrast, memory resting CD4 T cells (26% vs. 21%), M1 macrophages (5% vs. 3%), and M2 macrophages (13% vs. 11%) were enriched at higher levels in CD45+ tumor epithelium." (PMID 36230846, 2022). "A phase Ib trial combining a personalized neoAg vaccine with PD-1 blockade found durable, neoAg-specific CD4+ and CD8+ T cell responses in all 82 treated patients, and T cells migrated to metastatic tumors and mediated tumor cell killing." (PMID 35432319, 2022). "A recent study using a 89Zr-labeled anti-ICOS antibody in a lung cancer model detected activated CD4+ and CD8+ T cells in the tumor and tumor-draining lymph nodes in response to a STING immune agonist treatment." (PMID 35223381, 2022). "A major roadblock to improve the cross-talk between CD4+ T cells and CD8+ T cells is the immune suppressive action of tumor infiltrating T regulatory (Treg) cells." (PMID 36248808, 2022). "Administration of anti-CD8 antibody significantly reduced CD8+ cells in spleens and tumor-bearing SMG tissues in Atg5flox/flox mice, while the percentage of CD4+ cells remained unaffected." (PMID 35966597, 2022). "As the signature cytokine produced by CD4+ Th1 cells, IFN-γ can both directly mediate tumor rejection and recruit and activate innate and adaptive immune cells." (PMID 35874660, 2022). "The proportions of CD3+CD4+ and CD3+CD8+ cells varied between each tumour specimen and also showed variation within certain patients, where 2 tumour specimen, collected at different timepoints, were cultured." (PMID 35158816, 2022).
tumor (continued). "It was noticed that immune cells, especially DC cells, monocytes, CD4 + T cells, CD8 + T cells, NK cells, and gdT cells, were highly enriched in tumor tissues (HPV-TIL and HPV + TIL)." (PMID 36157879, 2022). "In general, if patients responding to ICIs show a higher abundance of Faecalibacterium and Ruminococcaceae, the number of CD4+ T cells and CD8+ T cells will increase, resulting in an overall better anti-tumor effect." (PMID 36466873, 2022). "In contrast, PD-1 expression, especially the percentage of PD-1high cells, which are functionally impaired in many cases, of CD4+ and CD8+ T cells, was significantly increased in the HFD-fed tumor-bearing mice." (PMID 36611881, 2022). "It seems that the local intra-tumor IFNγ production by tumor-infiltrated NK, CD4 Th1, and CD8 cytotoxic T lymphocytes together with TNFα supported the generation of high levels of specific antitumor CTLs leading to tumor growth suppression." (PMID 35736195, 2022). "Significant immune upregulation by CA alone was obtained in three areas: tumor size change ratio on day 14, ELISPOT assay, and CD4+ cell counts in immunostaining." (PMID 36012709, 2022). "The favourable effect of tumour-infiltrating lymphocytes (TILs) on patient outcome is well established in CRC, whose immunogenicity has been demonstrated by the tumour-selective activation of CD8+ and the migration of CD4+ T helper cells." (PMID 36497365, 2022). "Another group has developed a chimeric heavy-chain antibody targeting cells expressing CTLA-4, such as Tregs and CD4 helper T cells, and reported an induction of the cytokine IFN-γ, whose pleiotropic actions include anti-tumor activity." (PMID 36686160, 2022). "Analysis of CD8+ cytotoxic T cells (Tc-cells) demonstrated that, like the CD4+ T helper cells, there was an increase in the total number of CD8+ Tc-cells in control tumors, with these Tc-cells primarily restricted to the tumor stroma (p = 0.017)." (PMID 35565427, 2022). "While SLP with CpG adjuvants stimulated CD4+ T cells, the combination of lipoplexes and SLPs resulted in elevated stimulation of CD4+ and CD8+ T cells and better tumor suppression." (PMID 35014625, 2022). "It is important to remember that PD-L1 is expressed on both neoplastic and tumor-infiltrating immune cells, including macrophages; on the other hand, PD-1 is expressed on CD8+ and CD4+ T-cells, B-cells, and natural killer (NK) cells." (PMID 35743435, 2022). "Probably as a result of the induction of ICD and proinflammatory IFNγ, the XVir-N-31 injected tumors showed an increased infiltration of activated CD4+ and CD8+ T lymphocytes and a massive reduction in the tumor growth." (PMID 36077380, 2022). "FAM46C was positively correlated with the abundance of CD4+ T cells, CD8+ T cells and plasma B lymphocytes in the tumour microenvironment." (PMID 35222533, 2022). "T-cell infiltration was most commonly observed in the area surrounding the tumor, with a higher proportion of CD8+ T cells, compared to CD4+ T cells." (PMID 36497475, 2022). "For example, miR-142-5p overexpression inhibits pancreatic cancer growth by targeting PD-L1 expression on tumor cells, resulting in an increase in IFN- and TNF-, an increase in CD4+ and CD8+ T lymphocytes, and a decrease in PD-1 T lymphocytes." (PMID 36612180, 2022). "In this experiment, the DC vaccine based on PDT was shown to increase the number and activity of CD4+ T cells and CD8+ T cells in tumor tissue." (PMID 35832074, 2022). "Th2 is one of the special subtypes of CD4+ helper T cell (Th cell) that mainly secretes cytokines such as IL-4, IL-5, and IL-10, and excessive Th2 cells could affect the tumour-suppressive immune microenvironment, seriously reducing the anti-tumour effect, leading to the malignant growth of tumours." (PMID 35591854, 2022). "Our findings revealed that the proportion of CD3+ CD8+ T cells in Tumor-infiltrating T lymphocytes (TILS), is dramatically reduced after Tmem176b knockout, the same trend can be seen in CD3+ CD4+ T cells." (PMID 35399535, 2022).
tumor (continued). "In malignancies, they suppress the T-cell-mediated cytotoxicity of CD4+ and CD8+ cells to shelter tumor cells from immune elimination." (PMID 35433427, 2022). "Meanwhile, tumor-infiltrating T lymphocytes (TILs) also include a population of regulatory T (Treg) cells, a subset of CD4+ T cells, which accumulate in TIME and suppress tumor-specific T-cell responses." (PMID 35874784, 2022). "Several populations of tumor-infiltrating lymphocytes (TILs), such as CD4+ T helper (Th), CD8+ T cytotoxic (Tcyt), and regulatory CD4+CD25+FoxP3+ T-cells (Tregs) are found in the GBM TME." (PMID 36140392, 2022). "ADAM17 (a disintegrin and metalloproteinase domain 17), expressed on MDSCs, is likely to down-regulate L-selection on CD4+ and CD8+ T cells and prevent them to migrate to peripheral lymph nodes and tumor sites." (PMID 35053426, 2022). "Our data showed that Aza-cell-106 combined with reparixin increased the amounts of CD4+ T cells and CD8+ T cells in the tumor tissue, indicating that the therapeutic effect of Aza-cell-106 was enhanced by regulating the tumor immune microenvironment." (PMID 35805071, 2022). "Previous study has demonstrated that the CD4+ T cells can positively regulate the function of CTL by enhancement of CTL activity, migratory, and survival at tumor site." (PMID 35523765, 2022). "Contrary to the event of tumor-infiltrating CD8+ T cells, patients with high CD4+ T-cell infiltration had worse OS compared with those with low CD4+ T-cell infiltration." (PMID 36238304, 2022). "cDC1s mediate anti-tumor immunity by activating cytotoxic CD8+ T cells, cDC2s activate anti-tumor CD4+ T cells but this process is restricted by Tregs or other immunosuppressive factors." (PMID 36172157, 2022). "The levels of CD4+ and CD8+ T cells in the blood, spleen, and tumor of mice were determined using a flow cytometer." (PMID 35694271, 2022). "ACT using antigen-specific TILs is a personalized cancer treatment based on isolation of autologous CD4+ and CD8+ T cells from the tumor, ex vivo expansion and selection before reinfusion back to the patients to eliminate cancer cells." (PMID 35008422, 2022). "An increased infiltration of CD3+ T cells, CD4+ T cells, and CD8+ T cells in the tumor center has been shown to correlate with poor prognosis." (PMID 36010256, 2022). "We evaluated the abundance of six immune cell populations in the tumor microenvironment of the SKCM patients collected inside the TCGA cohorts: B cells, CD4 + T cells, CD8 + T cells, Neutrophils, Macrophages, and Dendritic Cells." (PMID 35725560, 2022). "One suggested mechanism is that tumor-specific antigens, processed via antigen presenting cells, are presented to T-cells which then activate CD8+ cytotoxic T-cells and CD4+ helper T-cells, which then infiltrate in the tumor." (PMID 35557956, 2022). "The anti-tumor activity of AN3025 was dependent on the infiltration of CD4+ and CD8+ T cells, as depletion of CD4+ and CD8+ T cells abolished the anti-tumor activity of AN3025." (PMID 35251028, 2022). "cDC1s are able to present tumor antigens to CD8+ T cells and to promote Th1 cell polarization of CD4+ T cells." (PMID 36275666, 2022). "Further, a significant increase in IFN-γ+IL-2+ double cytokine production by both tumor-infiltrating CD8+and CD4+ was obtained in the Lm-LLO-CD105A treated group in comparison to the Control Lm treated group." (PMID 36439126, 2022). "For the anti-tumor response, TCR activation in CD4+ T cells enables identification of neoantigens on tumor cells vs. normal cells and the fatal interaction of CD8+ T cells recognizing the tumor cells." (PMID 35174086, 2022). "Local infiltration of various immune cells such as CD3+ T cells, CD4+ T cells, CD8+ T cells, CD20+ B cells and macrophages in the tumor tissue were significantly increased." (PMID 36466825, 2022). "They preferentially localize in the tumor stroma in the vicinity of CD8+ and CD4+ T cells, B cells, and TLSs." (PMID 36230721, 2022).
tumor (continued). "The 13 patients enrolled in the study showed high rates of HER2-specific sensitization for both IFN-γ-secreting CD4+ T cells (85%) and CD8+ T cells (80%) and induction of tumor-lytic antibodies." (PMID 35154149, 2022). "The detection of relevant parameters in tumor tissues revealed increased PD-L1 and IFN-γ expression and enhanced tumor-infiltrating CD8+ and CD4+ T in the fascaplysin and anti-PD-1 combination therapy groups." (PMID 36430250, 2022). "CD4+ Th1 cells secrete IFN-γ and chemokines to promote the expansion and initiation of CD8+ T cells and their infiltration to the tumor site." (PMID 35680568, 2022). "Immune infiltration analyses revealed that “hot” tumors had a higher proportion of anti-tumor immune cells, such as CD8+ T cell, activated memory CD4+ T cell, gamma delta T cell, and M1 macrophage." (PMID 36588791, 2022). "Low doses of CpG injected into tumors induce OX40 expression on CD4+ T cells in the TME, while the anti-OX40 antibody triggers a T-cell immune response that is specific for the antigen of the injected tumor." (PMID 36365103, 2022). "In the Hdac5 knockdown group, anti-PD-1 treatment dramatically increased the tumor infiltration of CD45+CD8+ and CD45+CD4+ T cells as well as decreased the levels of CD11b+Gr1+ myeloid cells and CD4+Foxp3+ Treg cells in tumors." (PMID 35265200, 2022). "The results uncovered more activated memory CD4+ T cells, M1 macrophages (anti-tumor phenotype), and CD8+ T cells in low-CDIGPM group, but more M2 macrophages (pro-tumor phenotype) in high-CDIGPM group." (PMID 36341357, 2022). "The results showed that the fluorescence intensity and activation percentage of CD4+ T cells, CD8+ T cells, and DCs were significantly increased in tumor tissues following treatment with the Ce6-loaded BioPEGDMA@TPPM system." (PMID 35832074, 2022). "Current findings may be explained by a Treg subset of CD4+ T cells having cycled from cancer tissue into blood; alternatively, elevated levels of circulating cytokines such as IL-6, IL-10, and TGFβ may explain the tumor-suppressive profile in these blood samples." (PMID 35158758, 2022). "CD8+, CD4+ and CD20+ cells were located primarily in the stroma and were less prevalent in the tumour nest." (PMID 35982052, 2022). "The mechanism by which CD45RO+CCR6+CD4+ cells and granulocytes are recruited in TME is likely related to the presence of elevated amounts of IL-6 in tumor secretome from SD OSCC patients." (PMID 36713516, 2022). "The subpopulations of lymphocyte cells such as CD4 + and CD8 + T‐cells, gamma‐delta T‐cells, natural killer (NK) cells, and B‐cells have also been known to regulate the tumor progression." (PMID 36329394, 2022). "We also observed a similar immune cell infiltration profile in the A20 tumour model, where CAR(NAP) T-cell treatment led to higher infiltration of CD8+ T cells and Gr1+MPO+ neutrophils, and lower infiltration of FoxP3+CD4+ regulatory T cells." (PMID 35379957, 2022). "The authors further demonstrated that in the microenvironments containing CD4(+) CD73(+) T cells, B cells, or CD39(+) CD73(+) exosomes, CD73 is readily available to CD4(+) CD39(+) CD73(neg) Tregs for the production of tumor-promoting adenosine." (PMID 36233088, 2022). "Treg cells are able of suppressing tumor-specific effector cells, such as CD8+ cytotoxic T lymphocytes, CD4+ T helper lymphocytes and NKcells." (PMID 36068484, 2022). "Studies have found that the percentage of CD3+, CD4+, CD4+/CD8+, and NK cells in peripheral blood of NSCLC patients with stage IV was negatively correlated with the number of circulating tumor cells." (PMID 36051923, 2022). "To further explore the role of GINS4 in tumor immune, we determined the expression correlation of GINS4 with biomarkers of B cell, CD4 + T cell, neutrophil, dendritic cell and myeloid dendritic cell based on GEO datasets." (PMID 35365175, 2022).
tumor (continued). "Regulatory T cells, a suppressive subset of CD4+ T lymphocytes, can suppress immune reactions induced by CD8+ cytotoxic T lymphocytes to promote tumor escape." (PMID 34850589, 2022). "TILs such as CD3, CD4, CD5, and CD8, which attack cancer cells directly or contribute to antigen presentation, prevent tumor development in carcinogenesis." (PMID 36514573, 2022). "Regulatory T cells (Tregs; CD4+ FoxP3+ CD25+) are regulatory T cells that promote and maintain the immunosuppressive tumor microenvironment and can be activated by the immunosuppressive mediator, indoleamine 2,3 dioxygenase 1 (IDO1)." (PMID 36011015, 2022). "Herein, we aimed to detect the expression of CTLA-4, CD86, CD4, and CD8 in surgical specimens from RC patients after nCRT/nCT, and to classify CD4+ and CD8+ cells into stroma, tumor, and invasive categories according to their location." (PMID 36428666, 2022). "CD4+ helper T cells and cytotoxic CD8+ T cells can prevent tumor growth by targeting antigenic tumor cells, and high numbers of activated CD8+ T cells are associated with a good prognosis in GC and various cancers." (PMID 35874784, 2022). "As well as producing anti-tumor antibodies able to facilitate tumor killing through antibody-dependent cell cytotoxicity (ADCC), B cells are also able to present antigens to CD4+ T cells." (PMID 36003398, 2022). "For tumor immune cell infiltration, we found that SASH3 expression was positively correlated with the infiltration levels of T cell CD8+, T cell CD4+, Neutrophil, Myeloid dendritic cell, Macrophage, and B cell in 31 types of cancers." (PMID 35756681, 2022). "We clearly showed the reduction in CD4+ T cell number in the peripheral blood and GALTs in HFD-fed mice prior to tumor inoculation." (PMID 36611881, 2022). "DTYMK expression was positively correlated with tumor purity and infiltrating levels of B cells, CD8+ T cells, CD4+ T cells, macrophage, neutrophil, and dendritic cells in LIHC." (PMID 36159971, 2022). "To confirm that emergent dynamics follow experimental observations, we tested how outcomes vary as a function of four CAR and tumor features—CAR T-cell dose, CD4+:CD8+ CAR T-cell ratio, CAR-antigen affinity, and antigen density on cancer cells." (PMID 35903149, 2022). "We also found that the level of PD-1 expression on the T and B cells was significantly higher in the tumor samples, as compared to the lymph node samples, by a factor of 2.44 for CD19+ B cells, 1.76 for CD8+ T cells, and 1.94 for CD4+ T cells." (PMID 35158748, 2022). "Immunohistochemistry and flow cytometry were employed to detect the expression of PD-1, Treg cells, CD8, and CD68 in tumor tissues, and the contents of PD-1+ CD8+ T cells, PD-1+ CD4+ T cells, and PD-1+ Treg cells in the peripheral blood." (PMID 35619918, 2022). "Mature DCs expressed CCR7, which is necessary for the migration of tumor-infiltrating DCs into TDLNs where they process and load cancer antigens onto HLA-I and HLA-II for presentation to CD8+ T cells and CD4+ T cells, respectively." (PMID 36275666, 2022). "An increase in the level of Th CD4+ and CD8+ cells and a decrease in Tregs in the tumor microenvironment correlate with the abundance of Bifidobacterium, Faecalibacterium genus Ruminococcaceae family and Clostridiales order in the gut." (PMID 36428677, 2022). "TILs such as CD4+ T cells and CD8+ T cells play an essential role in tumor metastasis, recurrence, and response rate to immunotherapy." (PMID 35892841, 2022). "These tumor-infiltrating lymphocyte CD4+ Th cells (CD4+ Th TILs) had a tissue-resident memory phenotype, were present in MHC class II–rich areas, and proliferated in the tumor, suggesting local antigen recognition." (PMID 35439168, 2022). "The virus antigen was presented through MHC I and class II to activate CD4+ and CD8+ T cells which stimulate the body to produce T-cell responses to produce tumor-specific immune responses for tumor regression." (PMID 35494032, 2022).